SOX2 (SRY-box transcription factor 2)
Diseases named in the same sentence as SOX2 in open-access papers (continued):
Sharing a sentence is not in itself a finding about the gene and the disease.
lung diseases (6 papers, 2017 to 2024). "Changes in the level of SOX2 during lung development leads to aberrant epithelial differentiation, as frequently associated with pediatric lung diseases, such as in congenital pulmonary airway malformation (CPAM) and congenital diaphragmatic hernia (CDH)." (PMID 35615634, 2022). "Mice with altered SOX2 expression levels display aberrant epithelial differentiation, a phenotype that is frequently associated with pediatric lung diseases, such as in congenital pulmonary airway malformation (CPAM) and congenital diaphragmatic hernia (CDH)." (PMID 35615634, 2022). "Given that hyperplasia of NE cells and defective clustering are associated with several lung diseases and NE function respectively, investigating the molecular mechanisms downstream of SOX2 and SOX21 may provide new insight in NE function and development of new therapeutic approaches." (PMID 36867267, 2023). "The transcriptional activity of SOX2 largely depends on its interaction with other proteins and the identification of SOX2-associating proteins may be important to understand this aberrant epithelial differentiation in pediatric lung diseases." (PMID 35615634, 2022). "We only observed SOX2+/p63+/KRT5+ cells in aged individuals with pulmonary disease and dysplastic airway-like structures." (PMID 37191411, 2023). "Nevertheless, these results suggest that loss of SOX2 may contribute to Wnt activation and TP63 expression in KRT5−/KRT17+ dysplastic cells of IPF and pathological remodeling in human lung disease." (PMID 38182591, 2024). "Additionally, we observed a reduced number of SOX2 positive cells and SOX2 expression in conducting airways with aging, especially in aged individuals with pulmonary disease." (PMID 37191411, 2023). "The human SOX2+SOX9+ cells they cultured could potentially be used to model pediatric lung diseases (such as bronchopulmonary dysplasia), which are thought to originate during lung development." (PMID 28806170, 2017). "The SOX2−/TP63+ Wnt-activated transcriptional signature of KRT5−/KRT17+ basaloid cells in IPF and SOX2− signature of KRT5−/KRT17+ basaloid cells in post-COVID-19 fibrosis suggest that loss of SOX2 expression may explain the formation of these distinct dysplastic lesions in lung disease." (PMID 38182591, 2024). "In the exchange zone, we detected SOX2+, p63+, and KRT5+ cells in aged individuals diagnosed with lung disease." (PMID 37191411, 2023). "The role of SOX2 and other SOX family members in human lung disease is largely unknown." (PMID 38182591, 2024). "Indeed, because human SOX2+SOX9+ cells are derived from embryonic lungs, they are likely to more faithfully reflect the epigenetic features of the embryonic cells that contribute to pediatric lung disease than cells derived from adult lung epithelial cells or iPSCs." (PMID 28806170, 2017).
odontogenic keratocysts (6 papers, 2020 to 2025). "Human odontogenic keratocysts are usually strongly SOX2-positive, resembling the expression in CAA." (PMID 34072517, 2021).
ovarian tumor (6 papers, 2015 to 2022). "Our results indicate that PRL-3 plays an important role in cell state transition of ovarian tumor cells to the cancer stem-like cells, possibly via SOX2 upregulation." (PMID 31887658, 2020). "Conversely, others generated lung and ovarian tumor cells that stably overexpress SOX2 and reported an elevated number of TIC when these cells were tested in limiting cell dilution tumor assays." (PMID 28388544, 2017). "The median SOX2 expression significantly decreased in the corresponding, fully established ovarian tumors (p < 2− 16, one-way ANOVA followed by Tukey's test)." (PMID 27492892, 2016). "The positive expression rates for Class III β-tubulin, Sox2, and Survivin in ovarian tumor tissues were 59.09 %, 61.82 % and 52.73 %, respectively." (PMID 26198101, 2015). "SOX2 studies in ovarian epithelial lesions revealed that SOX2 expression increased with malignant potential from benign, borderline to malignant ovarian tumors." (PMID 26258069, 2015). "Additionally, FOXK2 knockdown significantly reduced mRNA expression levels of stemness-associated TFs (SOX2, OCT4, and NANOG) and stemness marker ALDH1A1 in OC cell lines and primary cells dissociated from a human ovarian tumor." (PMID 35349489, 2022). "Interestingly, the percent of SOX2-positive cells differs between different ovarian tumor subtypes." (PMID 28388544, 2017).
pituitary adenomas (6 papers, 2010 to 2025). "Together, we conclude that a decrease in the gene dosage of Sox2 rescues the main phenotypes associated with p27 deficiency, namely, gigantism, pituitary hyperplasia, pituitary adenomas, and retinal abnormalities." (PMID 23217425, 2012). "OCT4 and SOX2 are established markers of embryonic and pituitary stem cells, and their presence in pituitary adenomas has also been demonstrated." (PMID 41017273, 2025). "The hPASCs were successfully isolated and cultured from gonadotrophic pituitary adenoma in vitro, which were identified as positive for generic stem cell markers (Sox2, Oct4, Nestin and CD133) via immunohistochemical staining." (PMID 36750863, 2023). "Consistent with our findings are extensive studies using single cells isolated from human pituitary adenomas to show increased expression of stem cell markers SOX2 and CXCR4." (PMID 36359740, 2022). "Hmga2-induced pituitary adenomas exhibit >5-fold downregulation of Sox2 compared with normal pituitary tissue." (PMID 20668695, 2010). "Immunohistochemical staining was commonly used for verification of tumor stem cells in pituitary adenoma; four generic markers, namely Sox2, CD133, Nestin and Oct4 were selected and showed immunopositivity in the cultured hPASCs, thus validating the properties of their stemness." (PMID 36750863, 2023).
sinonasal carcinoma (6 papers, 2013 to 2025). "More than one third of sinonasal carcinoma harbored SOX2 amplification, and these cases were more likely to relapse after primary therapy." (PMID 35055392, 2022). "Aim of this study was to investigate amplification and expression status of SOX2 in sinonasal carcinomas and to correlate the results with clinico-pathological data." (PMID 23544055, 2013). "This is the first study assessing SOX2 amplification and expression in a large cohort of sinonasal carcinomas." (PMID 23544055, 2013). "We therefore suggest that SNUCs are molecularly closely related to SCCs and INVCs and that these entities represent a subgroup of sinonasal carcinomas relying on SOX2 acquisition during oncogenesis." (PMID 23544055, 2013). "Patients with SOX2-amplified sinonasal carcinomas showed a significantly higher rate of tumor recurrences than SOX2 non-amplified tumors." (PMID 23544055, 2013). "Further studies performed on larger cohorts are needed to explore the value of SOX2 as a prognostic marker in sinonasal carcinoma." (PMID 23544055, 2013). "Furthermore, a higher incidence of recurrence was correlated with SOX2 amplification in sinonasal carcinomas, and rectal cancer patients with elevated SOX2 displayed significantly shorter disease-free survival following chemoradiotherapy." (PMID 28388544, 2017). "SOX2 amplification appears to identify sinonasal carcinomas that are more likely to relapse after primary therapy, suggesting that these patients might benefit from a more aggressive therapy regime." (PMID 23544055, 2013). "Studies reported thus far indicate that high SOX2 levels correlate with poor prognosis for patients with many different cancers, including breast, colorectal, esophageal, ovarian, prostate, and some lung tumors, as well as nasopharyngeal and sinonasal carcinoma." (PMID 28388544, 2017). "This indicates that SOX2 does not serve as a tumor stem cell marker in sinonasal carcinoma, but rather functions as a ubiquitously activated oncogene." (PMID 23544055, 2013).
small cell carcinoma (6 papers, 2016 to 2024). A neuroendocrine carcinoma composed of small malignant cells which are often said to resemble "oat cells" under the microscope. "SOX2 is likely responsible for the neuroendocrine (NE) feature of small cell carcinoma." (PMID 38595814, 2024). "Additionally, previous studies have examined the effect of SOX2 levels on small cell neuroendocrine carcinomas (NECs) in certain organs, and found that SOX2 possibly plays a vital role in small cell NEC progression in the endometrium, esophagus, and lung." (PMID 33789601, 2021). "Small cell carcinoma LuCaP 145.1 in the stem-like grouping expresses stem cell transcription factors (scTFs) such as the core quartet of LIN28A, NANOG, POU5F1, and SOX2, as well as a low level (10-fold less) of β2-microglobulin (B2M) compared to the levels by non-stem cells." (PMID 38595814, 2024). "Cancer de-differentiation transforms luminal-like (differentiated) adenocarcinoma into less luminal-like and more stem-like (undifferentiated) small cell carcinoma through a sequential activation of stem cell transcription factors (scTF) POU5F1, LIN28A, SOX2 and NANOG." (PMID 34911496, 2021). "Previously, we reported the presence of scTF LIN28A, NANOG, POU5F1 and SOX2 in a small cell carcinoma patient-derived xenograft (PDX) line LuCaP 145.1 but absent in adenocarcinoma PDX lines." (PMID 31146720, 2019). "Newly available non-adenocarcinoma/small cell carcinoma PDX LuCaP lines were analyzed for expression of stem cell transcription factors (scTF) LIN28A, NANOG, POU5F1, SOX2, which are responsible for reprogramming or de-differentiation." (PMID 31146720, 2019).
synovial sarcoma (6 papers, 2016 to 2025). "A recent report suggests that a SS18-SSX fusion protein containing SWI/SNF complex in synovial sarcoma cell lines leads to displacement of PRC2/EZH2 at SOX2 loci, resulting in loss of the repressive H3K27Me3 marks and increased SOX2 expression." (PMID 27391784, 2016). "SOX2 is uniformly expressed in synovial sarcoma and its expression is an essential requirement for proliferation of these cells." (PMID 27074562, 2016). "Several pathways have been implicated in synovial sarcoma, including altered ATF2-mediated transcription, aberrant cell cycle inhibition and modulation of SOX2 expression." (PMID 27391784, 2016). "This suggests either that PRC2 function at the SOX2 loci is already fully inhibited in translocation positive synovial sarcoma cells, and thus SOX2 expression cannot be upregulated any further, or that other mechanisms are regulating SOX2 expression." (PMID 27391784, 2016). "However, inferring its effect on upregulating pluripotency genes and in particular activation of SOX2 in other tumors raises an important question: Does inhibition of FOXM1 vicariously targets SOX2 in synovial sarcoma?" (PMID 27074562, 2016). "In a selected specific, SOX2 is uniformly expressed in synovial sarcoma." (PMID 27074562, 2016). "Representative downstream genes in the SNF5 pathway, Sox2 and ApoD, were significantly upregulated in eMCs expressing SS18-SSX1 and also in mouse synovial sarcomas." (PMID 32019274, 2020). "Compared with the control tissues (chronic synovitis), the mRNA expression of SOX-2, Nanog, OCT-4, LIF, LIFR and Ki-67 was significantly higher in the synovial sarcoma tissue samples (P = 0.0070, P = 0.0487, P = 0.0002, P = 0.0110, P < 0.0001, and P = 0.0011, respectively)." (PMID 35151264, 2022). "We observed that EZH2 inhibition did not lead to a significant change in SOX2 expression in any of the synovial sarcoma cell lines examined." (PMID 27391784, 2016). "Thus, EZH2 inhibition does not change SOX2 expression in SS18-SSX positive synovial sarcoma cell lines, but is able to reverse some synovial sarcoma-specific gene expression, at least ATF3, and others less consistently across models." (PMID 27391784, 2016).
yolk sac tumor (6 papers, 2010 to 2026). A non-seminomatous malignant germ cell tumor composed of primitive germ cells. "Tissues were also stained for CDX2, SOX2 and FOXA2, which were negative in accordance with the absence of yolk sac tumors (YST) and EC." (PMID 38097681, 2024).
asthma (5 papers, 2019 to 2024). "Inhibiting FGFR1 has been shown to downregulate the expression of genes associated with asthma pathogenesis, including SOX2, a marker of epithelial-mesenchymal transition (EMT), as well as the mesenchymal markers N-cadherin and Vimentin." (PMID 39377013, 2024). "After adjusting for age, exposure to second-hand smoke (SHS), exercise, drinking, body fat, BMI, waist-hip ratio (WHR), asthma, and emphysema, SOX2 promoter methylation was significantly hypermethylated in both men and women residing in central and southern areas compared with the northern areas." (PMID 30867047, 2019). "There are two FDA-approved drugs that target GLI1/2; however, ciclesonide was initially approved for treatment of asthma, and its mechanism of inhibiting GLI1/2/SOX2 expression is unknown." (PMID 38920995, 2024).
basal cell carcinoma (5 papers, 2017 to 2024). A carcinoma involving the basal cells. "Of note, Basal Cell Carcinoma Signaling is closely related to Sonic Hedgehog (SHH) Signaling, which has been associated with the carcinogenesis of SCCs of the oral mucosa, uterine cervix, esophagus and lung, where it may have a role in mediating stemness via transcription factors like SOX2." (PMID 28787442, 2017).
bladder tumors (5 papers, 2020 to 2024). "Immunohistochemistry was used to verify SOX2 expression in primary bladder tumors, which showed SOX2 expression was high in tumors with “poorly differentiated” malignant grade." (PMID 32427884, 2020). "In the context of gemcitabine, the 5637GR bladder tumors had elevated expression of the OVOL1 target genes, including SOX2 and SOX9, in a OXCT1-dependent manner, resulting in greater mitotic index." (PMID 39509334, 2024). "We confirmed that SOX4, but not SOX2, was mainly amplified in primary bladder tumors." (PMID 32427884, 2020). "However, among the sixteen biomarkers, seven of them, namely LINC00355, UCA1-203, HOX-AS-2, Linc-ROR, OCT4, SOX2 and OTX2-AS1, did not demonstrate sufficient discriminatory power to separate bladder tumors from urocystitis, as indicated by their low AUC values (AUC<0.70)." (PMID 31949480, 2020).
choriocarcinoma (5 papers, 2010 to 2020). An aggressive malignant tumor arising from trophoblastic cells. "Recently, our team was the first to report loss of SOX2 and hypermethylation in the promoter region of SOX2 in trophoblastic diseases including hydatidiform mole and choriocarcinoma." (PMID 20814443, 2010). "Moreover, it has been significantly associated with reduced expression of SOX2 RNA in choriocarcinoma and hydatidiform mole." (PMID 30867047, 2019). "Thus, we considered that there was an association between Sox2 expression and malignancy in human choriocarcinoma." (PMID 23251245, 2013). "In studies of human choriocarcinoma, it was observed that expressed levels of Sox2 in human gestational trophoblastic neoplasia cells were higher than in the normal trophoblast cells." (PMID 23251245, 2013). "However, it is clear that miR-145 and Sox2 play potentially important roles in the pathogenesis of human choriocarcinomas." (PMID 23251245, 2013). "Therefore, we investigated whether the expression of endogenous Sox2 in human choriocarcinoma was silenced when the miR-145 overexpression might weaken the proliferation and invasion of carcinoma." (PMID 23251245, 2013). "Therefore, endogenous mature miR-145 expression may have an important role in the pathogenesis of human choriocarcinomas via interference with the Sox2 target gene by epigenetic modification." (PMID 23251245, 2013). "In view of this evidence, in the current study, the miR-145 expression vector was transfected into the human choriocarcinoma cell lines JAR and JEG-3 to determine its specific role in Sox2 regulation and inhibition of cell proliferation, and invasion." (PMID 23251245, 2013).
depression (5 papers, 2019 to 2025). "On the one hand, while the depression group showed higher scores on the HDRSe scale, their levels of specific proteins, such as Sox2 and Tubulin beta-III, significantly decreased compared to the control and BPD groups." (PMID 38654728, 2024). "Collectively, our data demonstrate that abolishing SOX2 expression in GABAergic neurons of the SCN perturbs behaviors that are associated with anxiety, depression, and motivation (or anhedonia) in mice." (PMID 34842772, 2021).
gastric adenocarcinoma (5 papers, 2012 to 2025). "In the research presented here, the influence of the level of mRNA expression of transcription factor SOX2 in the sub-set of gastric adenocarcinomas with over-expression of CDX2 was examined." (PMID 40149431, 2025). "SOX2 has been shown to be downregulated in intestinal metaplasia in the stomach, and its expression was demonstrated in gastric adenocarcinoma with both gastric and mixed phenotype." (PMID 22482081, 2012). "The current investigation examines gastric adenocarcinomas that have acquired CDX2 mRNA up-regulation for their concomitant expression of SOX2 and compares CDX2 up-regulated cancers that maintained SOX2 expression with CDX2 up-regulated cancers that have acquired concomitant SOX2 suppression." (PMID 40149431, 2025). "Sox2 is a primary regulator of gastric differentiation that maintains gastric mucosal features and regulates the expression of gastric mucus genes, such as Muc5ac, and it is downregulated during the development of gastric adenocarcinoma." (PMID 26839577, 2016). "Saffron extract at concentrations of 20, 40 and 100 μg/ml applied for 24, 48 and 72 hours reduced the expression self-renewal genes such as OCT4, KLF, SOX2, NANOG, and nucleostemin in gastric adenocarcinoma tumor cell line." (PMID 32711409, 2020).
Hearing impairment (5 papers, 2014 to 2024). A decreased magnitude of the sensory perception of sound. "We investigated the roles of Sox2 in cochlear hair cells, which are terminally differentiated cells, using conditional transgenic mice and several hearing loss models." (PMID 35227273, 2022). "The noise-induced threshold shifts in Prestin-Sox2OE mice were significantly lower at all frequencies compared with those of the control mice (p < 0.05), suggesting that Sox2 overexpression in OHCs protects against noise-induced hearing loss." (PMID 35227273, 2022). "Mice with specific Sox2 hypomorphic mutations that affect inner ear expression have hearing impairment due to decreased HC and SC number, while mice with inner ear-specific Sox2 null mutations are completely deaf and have no HCs or SCs." (PMID 31276493, 2019). "Additionally, reduced SOX2 expression contributes to truncated semicircular canals, shortened cochleae, and hearing impairment." (PMID 38790272, 2024).
injury (5 papers, 2016 to 2024). Damage inflicted on the body as the direct or indirect result of an external force, with or without disruption of structural continuity. "After acute viral lung injury, loss of Sox2 enhances airway-to-alveolar epithelial fate transition and formation of Krt5+ dysplastic regeneration." (PMID 38182591, 2024). "Therefore, it is conceivable that SOX2-induced expression of HERV-K might impact CNS development, maintenance of neural stem cells, remyelination, or recovery from nerve injury." (PMID 35420440, 2022).